MAGED4B (MAGE family member D4B)
Description:
May enhance ubiquitin ligase activity of RING-type zinc finger-containing E3 ubiquitin-protein ligases. Proposed to act through recruitment and/or stabilization of the Ubl-conjugating enzyme (E2) at the E3:substrate complex.
Gene: Protein-coding gene on chromosome X (52,061,827 to 52,069,272, reverse strand). Ensembl gene ENSG00000187243.
Gene Ontology:
Molecular function: protein binding
Biological process: negative regulation of transcription by RNA polymerase II
Cellular component: nucleus
Homologues: Orthologues: chimpanzee MAGED4 (99% identical), macaque MAGED1 (98% identical), zebrafish ndnl2 (13% identical), Drosophila melanogaster MAGE (8% identical). Paralogues in human: MAGED4 (100% identical), MAGED1 (43% identical), TRO (35% identical), MAGED2 (30% identical), MAGEL2 (22% identical), MAGEE1 (18% identical), MAGEB4 (17% identical), MAGEB17 (17% identical), MAGEB18 (16% identical), MAGEB1 (16% identical), MAGEB10 (16% identical), MAGEB2 (16% identical), and 25 more.
Diseases named in the same sentence as MAGED4B in open-access papers:
MAGED4B is named in the same sentence as 8 diseases in open-access papers, as found by Europe PMC text mining. Sharing a sentence is not in itself a finding about the gene and the disease. The quoted sentences say what the papers report.
glioma (1 paper, 2020). A benign or malignant brain and spinal cord tumor that arises from glial cells (astrocytes, oligodendrocytes, ependymal cells). "Interestingly, Oncomine analysis revealed that in glioma, several MAGE genes, including MAGED1, MAGED4, and MAGED4B exhibited elevated expression." (PMID 33425727, 2020).
hepatocellular carcinoma (1 paper, 2015). A malignant tumor that arises from hepatocytes. "For MAGED4B, its overexpression has been linked to malignant tumors and poor patient outcome in many types of cancer including breast, oral squamous cell carcinoma, and hepatocellular carcinoma." (PMID 26060332, 2015).
melanoma (1 paper, 2021). A malignant, usually aggressive tumor composed of atypical, neoplastic melanocytes. "MAGED4B-specific CD8+T cells were identified in 4/4 HLA-A2pos patients from the Malaysian cohort and 8/11 HLA-A2pos patients from the UK cohort at a frequency observed at a similar level to neoepitopes in melanoma (range 0.06-0.12%)." (PMID 34733290, 2021).
tumor (5 papers, 2016 to 2023). "E-protein promotes MAGED4 and MAGED4B (melanoma antigen family members) which have tumor antigenic properties and elicit T-cell responses against tumor/tissue cells." (PMID 35723340, 2022). "We subsequently examined the protein expression of MAGED4B and FJX1 in HNSCC tumour tissues from both Malaysian and UK cohorts by IHC." (PMID 34733290, 2021). "Using TCGA-HNSC project data, we demonstrated that both MAGED4B and FJX1 gene expression levels in the HPV negative (n=415) and HPV positive (n=72) tumour tissue samples were significantly higher than levels in adjacent normal tissues (n=44)." (PMID 34733290, 2021).
MAGED4B also shares sentences with these, for which no sentence is quoted: cancer (2 papers); head and neck squamous cell carcinoma (1); oral squamous cell carcinoma (1); triple-negative breast carcinoma (1).